OTOP2 (otopetrin 2)
Description:
Proton-selective ion channel open at neutral pH. Active at neutral and alkaline extracellular pH, likely participates in some alkali-related physiological activities.
Tractability: Antibody: UniProt places it where antibodies can reach, with medium confidence; UniProt predicts a signal peptide or a membrane-spanning region; its Gene Ontology location is reachable by antibodies, with medium confidence; the Human Protein Atlas places it where antibodies can reach.
Gene: Protein-coding gene on chromosome 17 (74,922,950 to 74,933,912, forward strand). Ensembl gene ENSG00000183034.
Subcellular location: Cell membrane
Subcellular location (Human Protein Atlas): Plasma membrane
Gene Ontology:
Molecular function: protein binding; proton channel activity
Biological process: proton transmembrane transport
Cellular component: plasma membrane; membrane
Genetic constraint (gnomAD): Loss-of-function variants: 41 observed, 46.29 expected, observed/expected ratio (o/e) 0.89, 90% interval 0.69 to 1.15. The upper end of that interval is the gene's LOEUF score, 1.15, which puts it in group 5 of 6, group 1 being the genes least tolerant of losing a copy. Missense variants: 721 observed, 774.72 expected, observed/expected ratio (o/e) 0.93, 90% interval 0.88 to 0.99. Synonymous variants: 328 observed, 330.2 expected, observed/expected ratio (o/e) 0.99, 90% interval 0.91 to 1.09.
Homologues: Orthologues: chimpanzee OTOP2 (98% identical), macaque OTOP2 (94% identical), dog OTOP2 (87% identical), pig OTOP2 (86% identical), mouse Otop2 (85% identical), rat Otop2 (85% identical), guinea pig OTOP2 (83% identical), rabbit OTOP2 (79% identical), tropical clawed frog otop2 (49% identical), zebrafish otop2 (42% identical), Caenorhabditis elegans otpl-3 (19% identical), Caenorhabditis elegans otpl-7 (18% identical), and 4 more. Paralogues in human: OTOP3 (40% identical), OTOP1 (33% identical).
Diseases named in the same sentence as OTOP2 in open-access papers:
OTOP2 is named in the same sentence as 16 diseases in open-access papers, as found by Europe PMC text mining. Sharing a sentence is not in itself a finding about the gene and the disease. The quoted sentences say what the papers report.
colorectal cancer (8 papers, 2019 to 2024). A primary or metastatic malignant neoplasm that affects the colon or rectum. "OTOP2 was proved to be involved in proton channel activity, which is consistent with our biological problem of interest as the colorectal cancer disease is closely related to electrolyte changes." (PMID 38993634, 2024). "We also identified multiple down-regulated genes in colorectal cancer that are supported by recent studies on the gene products of the OTOP2, OTOP3, SPIB, and INSL5 genes." (PMID 37790614, 2023). "In colorectal cancer and inflammation loss of BEST4/OTOP2 cells has been described." (PMID 37543577, 2023). "Proton-selective channel OTOP2 also acts a tumor suppressor gene in colorectal cancer." (PMID 35511361, 2022).
colon cancer (3 papers, 2019 to 2023). "We thereby identified FGFR2, MMP11 and OTOP2 as three differentially expressed genes in the neoplastic tissue predicting tumour recurrence in stage II colon cancer." (PMID 37543577, 2023). "This is especially true for the three identified genes, MMP11, FGFR2 and OTOP2, which need validation in an equivalent stage II colon cancer cohort with conventional immunostaining procedures." (PMID 37543577, 2023). "Three differentially expressed genes (FGFR2, MMP11 and OTOP2) in the neoplastic tissue compartments of relapsed patients in comparison to non-relapsed patients were identified predicting recurrence in stage II colon cancer." (PMID 37543577, 2023). "We were able to identify FGFR2, MMP11 and OTOP2 as upregulated genes in tumour compartments of relapsed patients diagnosed with stage II colon cancer." (PMID 37543577, 2023). "In our study we observed that OTOP2 is overexpressed in relapsed stage II colon cancer patients." (PMID 37543577, 2023). "This proof of principle study shows the potential of in situ sequencing revealing novel potential predictive biomarkers in colon cancer stage II, namely MMP11, FGFR2 and OTOP2, relevant for relapse of disease." (PMID 37543577, 2023).
colon adenocarcinoma (2 papers, 2019 to 2024). "Although the role of OTOP2 in tumor suppression has been reported in several studies of colon adenocarcinoma (COAD), characterized its immunomodulatory effects on tumors." (PMID 39132149, 2024).
colitis (1 paper, 2026). Inflammation of the colon. "Accordingly, Otop2-/- mice exhibit increased susceptibility to dextran sulfate sodium (DSS)-induced colitis." (PMID 42103221, 2026).
deafness (1 paper, 2011). An inherited or acquired condition characterized by the complete loss of the ability to hear from one or both ears. "We also extended our evolutionary studies to the Ush1g deafness gene because of the tight head-to-tail physical clustering of Ush1g with Otop2 and Otop3 in vertebrate genomes, and because mutations in Otop1 and Ush1g result in inner ear phenotypes in vertebrates." (PMID 21261979, 2011).
enteritis (1 paper, 2024). Inflammation of the small intestine. "Among them, OTOP2 is conserved among species, is expressed in various tissues, and plays an important role in diseases of the gustatory and digestive systems; for example, high OTOP2 mutation can induce enteritis and COAD9, 10-13." (PMID 39132149, 2024).
esophageal cancer (1 paper, 2024). A primary or metastatic malignant neoplasm involving the esophagus. "We then developed a blood-based methylation assay targeting OTOP2 and KCNA3 (named “IEsohunter”) for esophageal cancer noninvasive detection." (PMID 38890756, 2024).
esophageal squamous cell carcinoma (1 paper, 2024). Esophageal squamous cell carcinoma (ESCC) is a type of esophageal carcinoma (EC) that can affect any part of the esophagus, but is usually located in the upper or middle third. "Plasma methylated OTOP2 and KCNA3 cycle threshold (Ct) values were significantly lower in patients with esophageal squamous cell carcinoma (ESCC) than in all controls (P < 0.0001)." (PMID 38890756, 2024).
hearing loss (1 paper, 2023). "A fourth rare variant, c.379A>G (p.(Ser127Gly)), was found within OTOP2, a gene which maps to the candidate region of Usher syndrome 1G (USH1G), which includes congenital hearing loss, vestibular areflexia, and adolescent-onset retinitis pigmentosa." (PMID 37107589, 2023).
Meniere disease (1 paper, 2023). A disease of the inner ear (labyrinth) that is characterized by fluctuating sensorineural hearing loss; tinnitus; episodic vertigo; and aural fullness. "Rare variants within ECM1, OTOP1, and OTOP2 were each identified in three adult patients with Meniere’s disease." (PMID 37107589, 2023). "Three genes, ECM1, OTOP1, and OTOP2, harbored rare variants in Spanish patients with Meniere’s disease." (PMID 37107589, 2023). "Within OTOP2, the c.760G>A (p.(Ala254Thr)) variant was identified in a sporadic patient with Meniere’s disease since early adulthood." (PMID 37107589, 2023).
ulcerative colitis (1 paper, 2024). An inflammatory bowel disease involving the mucosal surface of the large intestine and rectum. "However, its functions and related mechanisms in tumors have rarely been reported until recently, when relatively low expression of OTOP2 was observed in ulcerative colitis and throughout the progression to COAD compared with that in normal intestinal epithelium." (PMID 39132149, 2024).
tumor (6 papers, 2019 to 2025). "Most importantly, for the first time, we revealed a close association between OTOP2 expression and the tumor immune micro-environment." (PMID 39132149, 2024). "In COAD, in vitro studies showed that OTOP2 suppressed the proliferation, migration, invasion, and adhesion of tumor cells." (PMID 39132149, 2024). "In COAD, in vitro studies showed that OTOP2 suppressed the growth, movement, penetration, and attachment of tumor cells." (PMID 39132149, 2024). "Our research showed that OTOP2 functions as a tumor suppressor in COAD, suggesting its potential as a prognostic biomarker for patients with this condition." (PMID 39132149, 2024). "Using the TCGA database, we compared the mRNA expression of OTOP2 between tumor and normal tissue specimens from 33 kinds of tumors." (PMID 39132149, 2024). "Here, we report that OTOP2 is down‐regulated in cancerous tissues and that elevated OTOP2 effectively suppresses tumor proliferation in vitro." (PMID 30652071, 2019). "This study highlighted the close connection between OTOP2 and components of the tumor immune microenvironment, suggesting that patients with high OTOP2 expression in COAD could benefit from immunotherapy." (PMID 39132149, 2024). "We conducted in vitro assays to demonstrate the tumor suppressive effect of OTOP2 in COAD cells." (PMID 39132149, 2024). "Some research has suggested that OTOP2 could function as a gene that inhibits tumor growth in COAD." (PMID 39132149, 2024). "Based on these results, we hypothesized that OTOP2 in COAD cells might modulate the expression and function of MHC-I and further affect the recognition and killing effects of CD8+ T cell on tumor cells." (PMID 39132149, 2024).
cancer (4 papers, 2019 to 2024). A tumor composed of atypical neoplastic, often pleomorphic cells that invade other tissues. "For example, C0 FXYD5+ TCs are abundantly present in cancerous tissues, whereas C2 MUC2+ TCs and C4 OTOP2+ TCs are predominantly present in normal and para-cancer tissues." (PMID 39717768, 2024). "Using CRC data taken from The Cancer Genome Atlas, we determined that the expression of otopetrin 2 (OTOP2) is highly correlated with malignancy grade and rate of patient survival." (PMID 30652071, 2019). "This study not only demonstrated that OTOP2 could inhibit cell proliferation, invasion, and migration, but also reduced cancer cell adhesion." (PMID 39132149, 2024). "The gene OTOP2 has been identified as a TSG, as it was significantly downregulated in the cancer phenotype." (PMID 39484215, 2024).
infection (1 paper, 2024). The state of being infected such as from the introduction of a foreign agent such as serum, vaccine, antigenic substance or organism. "Similarly, the promoter region of OTOP2 and USH1G (nearby genes on sense and antisense strands) with increased accessibility (infection-biased OCRs) had concurrently modest increased gene expression." (PMID 38862613, 2024).
OTOP2 also shares sentences with these, for which no sentence is quoted: adenoma (1 paper); lung squamous cell cancer (1).